SCGN (secretagogin, EF-hand calcium binding protein)
Synonyms: SECRET; DJ501N12.8; SEGN; CALBL; setagin
Tractability: Small molecule: a structure with a bound ligand is known. Antibody: UniProt places it where antibodies can reach, with medium confidence; its Gene Ontology location is reachable by antibodies, with medium confidence. PROTAC: its protein half-life has been measured.
Gene: Protein-coding gene on chromosome 6 (25,652,201 to 25,701,783, forward strand). Ensembl gene ENSG00000079689.
Subcellular location: Cytoplasm; Secreted; Cytoplasmic vesicle, secretory vesicle membrane
Subcellular location (Human Protein Atlas): Cytosol
Gene Ontology:
Molecular function: protein binding; calcium ion binding
Cellular component: cytosol; cytoplasm; dendrite; nucleus; synapse; terminal bouton; extracellular region; transport vesicle membrane
Genetic constraint (gnomAD): Loss-of-function variants: 17 observed, 18.54 expected, observed/expected ratio (o/e) 0.92, 90% interval 0.63 to 1.38. The upper end of that interval is the gene's LOEUF score, 1.38, which puts it in group 5 of 6, group 1 being the genes least tolerant of losing a copy. Missense variants: 209 observed, 220.72 expected, observed/expected ratio (o/e) 0.95, 90% interval 0.85 to 1.06. Synonymous variants: 75 observed, 76.23 expected, observed/expected ratio (o/e) 0.98, 90% interval 0.82 to 1.19.
Homologues: Orthologues: chimpanzee SCGN (99% identical), macaque SCGN (97% identical), guinea pig SCGN (87% identical), dog SCGN (86% identical), rabbit SCGN (85% identical), mouse Scgn (85% identical), pig SCGN (84% identical), rat Scgn (84% identical), tropical clawed frog scgn (74% identical), zebrafish scgn (73% identical), Drosophila melanogaster Cbp53E (46% identical). Paralogues in human: CALB2 (38% identical), CALB1 (36% identical).
Diseases named in the same sentence as SCGN in open-access papers:
SCGN is named in the same sentence as 32 diseases in open-access papers, as found by Europe PMC text mining. Sharing a sentence is not in itself a finding about the gene and the disease. The quoted sentences say what the papers report.
clear cell renal cell carcinoma (3 papers, 2014 to 2024). "In clear-cell renal cell carcinomas, expression of SCGN is associated with a high metastasis rate." (PMID 25226615, 2014). "Our previous studies found that secretagogin (SCGN) showed intranuclear aggregation in the early stages of clear cell renal cell carcinoma (ccRCC) development." (PMID 39664565, 2024).
diabetes (3 papers, 2020 to 2024). "Dysregulation of SCGN homeostasis is implicated in the progression of several pathophysiologies like diabetes, neurodegeneration, and cancer." (PMID 35870554, 2022). "Deregulated SCGN expression is reported in a broad range of disorders that include diabetes, neurodegenerative disorders, cancer, and ulcerative colitis." (PMID 35870554, 2022). "All significant correlations of ERS biomarkers with BMI, HbA1c, glucose, HOMA-B, and HOMA-IR point toward the clinical relevance of HSP70, GRP78, PRX1, PRX2, PRX4, PRX6, and SCGN, as they are not only elevated in patients with diabetes but also correlate with glucometabolic variables." (PMID 39765892, 2024). "The expression of SCGN is altered in several diseases, such as diabetes, cancers, and neurodegenerative disorders; however, the precise associations that closely link SCGN expression to such pathophysiologies are not known." (PMID 35870554, 2022). "The status of GDM, in contrast to type 2 diabetes mellitus, might, thus, not be the determining factor for differences in SCGN levels." (PMID 32708966, 2020).
Insulin resistance (3 papers, 2019 to 2024). Increased resistance towards insulin, that is, diminished effectiveness of insulin in reducing blood glucose levels. "Further, overexpression of SCGN has been shown to rescue neurodegeneration and insulin resistance." (PMID 35870554, 2022). "Low expression of SCGN is responsible for the progression of insulin resistance." (PMID 30678306, 2019).
Alzheimer disease (2 papers, 2022 to 2023). A progressive, neurodegenerative disease characterized by loss of function and death of nerve cells in several areas of the brain leading to loss of cognitive function such as memory and language. "In addition to Alzheimer’s disease, a deficiency in SCGN might be a risk factor for autism spectrum disorders." (PMID 37711587, 2023). "We provide a rationale for a direct interplay among the three: (i) cellular stress, (ii) deregulation of Ca2+ and/or SCGN expression levels, and (iii) protein misfolding diseases, such as Parkinson’s and Alzheimer’s disease." (PMID 35870554, 2022). "Finally, it is known that different calcium-binding proteins can influence the susceptibility of neurons to neurodegeneration, and considering the expression of SCGN in the hippocampus, it is not surprising that it plays a role in neuronal resistance in Alzheimer’s disease." (PMID 37711587, 2023).
autism spectrum disorder (2 papers, 2023). A spectrum of developmental disorders that includes autism, and Asperger syndrome. "It has recently been discovered that the interaction between SCGN and Doc2α (a protein related to autism spectrum disorders) plays an important role in neuronal morphology, glutamatergic transmission and different behaviors of mice, leading to abnormalities if such interaction is disrupted." (PMID 37711587, 2023).
colitis (2 papers, 2019 to 2023). Inflammation of the colon. "We show that the disease-causing mutation results in loss of SCGN function and that Scgn-deficient mice are predisposed to colitis, highlighting the role of this gene, and more broadly the role of the neuroendocrine intestinal compartment, in intestinal immune homeostasis." (PMID 31663849, 2019).
hepatocellular carcinoma (2 papers, 2023 to 2024). A malignant tumor that arises from hepatocytes. "In the context of cancer, SCGN has emerged as a novel marker for cervical neuroendocrine carcinoma and has been linked to sorafenib resistance in hepatocellular carcinoma." (PMID 38375034, 2024).
neuroendocrine tumor (2 papers, 2022 to 2025). "In humans, chromogranins, particularly chromogranin A and SCGN, are associated with secretory granules in neuroendocrine cells, and are biomarkers of neuroendocrine tumours and a variety of diseases." (PMID 40438247, 2025). "Both populations were also characterised by expression of chromogranin/secretogranin neuroendocrine tumour marker genes (e.g. CHGA, SCGN)." (PMID 40438247, 2025). "Among these, SCGN, CHGA and CADM1 are known neuroendocrine tumor markers, suggesting this proteotype is neuroendocrine-like." (PMID 35383171, 2022).
type 2 diabetes (2 papers, 2020 to 2025). "SCGN might play a different role in insulin secretion in patients with type 2 diabetes than in pregnancy and women with gestational diabetes." (PMID 32708966, 2020). "We measured plasma levels of SCGN and GIP in both fasting and postprandial states among nondiabetic healthy individuals and patients with type 2 diabetes." (PMID 40012909, 2025).
central neurocytoma (1 paper, 2014). A benign brain tumor composed of neural elements which most often arise from the SEPTUM PELLUCIDUM and the walls of the lateral ventricles. "Most interestingly, recent study shown that SCGN may be one of genes involved in tumorgenesis and progression in Central Neurocytomas (CNs)." (PMID 25226615, 2014).
colorectal carcinoma (1 paper, 2025). A malignant epithelial neoplasm that arises from the colon or rectum and invades through the muscularis mucosa into the submucosa. "Proteomic analysis of colorectal carcinoma revealed significant alterations in protein expression, with secretagogin (SCGN) downregulated and GRP78 upregulated in tumor tissues." (PMID 41458541, 2025).
gestational diabetes (1 paper, 2020). Carbohydrate intolerance first diagnosed during pregnancy. "Until now, no study on SCGN levels in pregnancy or patients with gestational diabetes mellitus (GDM) has been published." (PMID 32708966, 2020).
Hirschsprung disease (1 paper, 2025). Hirschsprung disease (HSCR) is a congenital intestinal motility disorder that is characterized by signs of intestinal obstruction due to the presence of an aganglionic segment of variable extent in the terminal part of the colon. "This study employs TMT-based proteomics to identify SCGN as a key regulator in Hirschsprung disease (HSCR)." (PMID 40653016, 2025).
kidney cancer (1 paper, 2024). Primary or metastatic malignant neoplasm involving the kidney. "SCGN protein is detected in kidney cancer samples but not in normal tissues." (PMID 38375034, 2024).
meningioma (1 paper, 2023). A generally slow growing tumor attached to the dura mater. "In total, 244 patients with meningiomas with tissue in TMAs were included and the IHC markers S100B, SCGN, ACADL and MCM2 were analyzed." (PMID 36685704, 2023). "Recently, the immunohistochemistry (IHC) markers S100B, SCGN, ACADL and MCM2 have been shown to be associated with underlying biological subtypes of meningioma (MG1-MG4)." (PMID 36685704, 2023).
metastatic tumors (1 paper, 2024). "Firstly, we compared the difference of mRNA expression of SCGN in primary and metastatic tumors in GSE22541 cohort." (PMID 38831128, 2024). "Since the expression of SCGN is gradually decreased with tumor progression, we wanted to know the expression status of SCGN in metastatic tumors of ccRCC." (PMID 38831128, 2024).
nicotine addiction (1 paper, 2022). "The PLG showed upregulated neural-related gene, i.e., neuronal acetylcholine receptor subunit alpha-7-like (CHRNA8) in the nicotine addiction pathway and secretagogin (SCGN) gene expression, as compared to the LG (p < 0.05)." (PMID 35268235, 2022).
protein misfolding diseases (1 paper, 2022). "To investigate how this process impacts the interaction of SCGN with client proteins, we selected α-synuclein, an intrinsically unstructured protein prone to aggregation and implicated in proteinopathy, and insulin known to interact with SCGN." (PMID 35870554, 2022). "To discern a correlation of SCGN expression with protein misfolding diseases, we first looked for alterations in the temporal expression of endogenous SCGN under stress conditions." (PMID 35870554, 2022). "We now identify chaperone activity as one of the crucial functions of SCGN vis-a-vis Ca2+ and elucidate why deregulated SCGN levels accelerate protein misfolding disorders." (PMID 35870554, 2022). "We describe a plausible mechanism of how perturbations in Ca2+ homeostasis and/or deregulated SCGN expression would hasten the process of protein misfolding, which is a feature of many aggregation-based proteinopathies." (PMID 35870554, 2022). "Thus, we identify a new role of SCGN as a Ca2+-dependent general chaperone and suggest its larger, yet unappreciated, involvement in precluding protein misfolding disorders." (PMID 35870554, 2022).
renal carcinoma (1 paper, 2022). A carcinoma arising from the epithelium of the renal parenchyma or the renal pelvis. "The consistent deregulated expression of SCGN leads to the proposition that SCGN could be considered a potential biomarker for certain cancers, such as prostate, large cell neuroendocrine, pituitary, colorectal, and renal cancers." (PMID 35870554, 2022).
ulcerative colitis (1 paper, 2019). An inflammatory bowel disease involving the mucosal surface of the large intestine and rectum. "In this study, we report the identification of an ultra rare missense variant (NM_006998.3:c.230G > A;p.Arg77His) in the SCGN gene causing Mendelian early-onset ulcerative colitis." (PMID 31663849, 2019). "In this study, we identified a homozygous recessive mutation in the SCGN gene causing early-onset ulcerative colitis." (PMID 31663849, 2019). "In this study, we identified a consanguineous family with recessive early-onset ulcerative colitis caused by a homozygous mutation in the SCGN gene." (PMID 31663849, 2019). "A mutation in SCGN is linked to early-onset ulcerative colitis." (PMID 31663849, 2019).
cancer (10 papers, 2012 to 2025). A tumor composed of atypical neoplastic, often pleomorphic cells that invade other tissues. "MMP9 and SCGN were poorly associated with microsatellite instability (MSI) in pan-cancer." (PMID 38375034, 2024). "MMP9 and SCGN were generally associated with OS in pan-cancer, including ccRCC." (PMID 38375034, 2024). "In addition, whether SCGN deficiency promotes the occurrence of epithelial-mesenchymal transition in ccRCC and confers the ability of cancer cells to metastasize distantly also deserves further in-depth investigation." (PMID 38831128, 2024). "In pan-cancer, both MMP9 and SCGN were associated with a variety of immune regulatory molecules, including chemokines, receptors, MHC molecules, immunosuppressive molecules, and immune activating molecules." (PMID 38375034, 2024). "To visualize the expression level of SCGN in pan-cancer, we performed a pan-cancer analysis of SCGN expression level in the TCGA database using UALCAN." (PMID 38831128, 2024). "In conclusion, our results suggest that reduced expression of SCGN in cancer cells is correlated with the progression and prognosis of ccRCC." (PMID 38831128, 2024). "Compared with normal tissues, the expression levels of MMP9 and SCGN generally changed in pan-cancer." (PMID 38375034, 2024). "In this paper, we investigated the differential expression of SCGN in cancer and normal tissues and evaluated its prognostic value." (PMID 38831128, 2024). "We initially analyzed the difference in protein expression of SCGN in cancer and normal tissues in the CPTAC database using the UALCAN website." (PMID 38831128, 2024). "SCGN was significantly highly expressed in the carcinomas and was heavily concentrated in the nucleus." (PMID 38831128, 2024). "In various cancers, MMP9 and SCGN were associated with immune-related molecules and immune cells." (PMID 38375034, 2024). "MMP9 and SCGN not only played regulatory roles in ccRCC, they had also shown value in pan-cancer." (PMID 38375034, 2024). "In pan-cancer, both MMP9 and SCGN were associated with multiple immune checkpoint molecules." (PMID 38375034, 2024). "Altogether, our data not only demonstrate that SCGN is a Ca2+-dependent generic molecular chaperone involved in protein homeostasis with broad substrate specificity but also elucidate the origin of its altered expression in several cancers." (PMID 35870554, 2022). "SCGN expression was localized in the cytoplasm of cancer cells." (PMID 25226615, 2014). "Finally, we also analyzed the roles of MMP9 and SCGN in pan-cancer." (PMID 38375034, 2024). "The reduction in cell viability induced by MIR494 has been observed in other cancer types; indeed, several MIR494 targets have been thus far identified which are associated with reduced cellular survival including IGF2, c-KIT, HOXA10, CLPTM1L, SCGN, CXCR4, and c-myc." (PMID 26794413, 2016). "Therefore, the focus of subsequent studies should be to explore whether the absence of SCGN leads to the loss of lipid droplets and the increase of mitochondria in cancer cells." (PMID 38831128, 2024). "The recent study indicated that LGALS3BP, MUC16, SCGN and SLC39A6 had abnormal expression in various cancer." (PMID 22438889, 2012). "It is also possible that the absence of SCGN leads to a decrease in lipid production in cancer cells, resulting in a relative increase in lipid droplets and mitochondria." (PMID 38831128, 2024). "The results of xenograft tumor experiments indicated that SCGN overexpression also did not affect cancer cell proliferation in vivo." (PMID 39664565, 2024). "Apart from that, overexpression of SCGN did not change the clone-forming ability of cancer cells." (PMID 39664565, 2024). "In this study, we found that SCGN did not affect the malignant phenotype of cancer cells, but could regulate cytokine/chemokine secretion and immune cell migration by performing gene function assays and RNA-seq analyses after overexpressing SCGN in cell lines of ccRCC." (PMID 39664565, 2024).
tumor (8 papers, 2022 to 2025). "The UMAP plots showed that the LHB, GNRHR, TGFBR3L, FOSB and SCGN genes were highly expressed mainly in the epithelial cells of the normal group, while their expression was low in the epithelial cells of the tumour group." (PMID 39548559, 2024). "Meanwhile, SCGN, which was overexpressed in tumor cells, underwent experimental validation, emphasizing its role in ccRCC." (PMID 38375034, 2024). "At both the mRNA and protein levels, the expression of SCGN in tumor tissues was higher than that in normal tissues, which was confirmed by IHC staining of HPA." (PMID 38375034, 2024). "Specifically, miR-494 targets secretagogin (SCGN), which is involved in the apoptosis processes of tumour cells." (PMID 38203731, 2023). "The expression of SCGN gene in HCC tumor tissues was significantly up-regulated (log2 fold change = 1.88, p < 0.01), while the expression level of RELN gene in HCC tumor tissues did not change significantly (log2 fold change = 0.84, p = 0.55)." (PMID 35034536, 2022). "We found that SCGN gene expression was up-regulated in HCC tumor tissues, but down-regulated in sorafenib-resistant HCC cells." (PMID 35034536, 2022). "Furthermore, SCGN has the potential to be used as a biomarker for routine detection in clinicopathology to assess tumor heterogeneity and patient’s prognosis." (PMID 38831128, 2024). "In addition, transwell experiments showed that the invasion ability of tumor cells was weakened after SCGN knockdown." (PMID 38375034, 2024). "Based on our previous findings that SCGN is specifically highly expressed in tumor tissues in the early stages of ccRCC 16, it could be used as a marker for ccRCC diagnosis, but whether it is specifically present in ccRCC but not in other types of RCC deserves further investigation." (PMID 39664565, 2024). "Specifically, NUCB2, SCGN and IFI6 were markedly upregulated in cells from the tumour centre, whereas COL5A2 was significantly downregulated in this region." (PMID 40913484, 2025). "In our study, we found that SCGN is highly expressed mainly at the early stage of tumorigenesis, and SCGN can upregulate TNFα at an early stage, by NF-ĸB creating an inflammatory TME and thus recruiting M1-type macrophages to inhibit tumor progression." (PMID 39664565, 2024). "It was found that SCGN was absent in all the normal kidney tissues and significantly overexpressed in ccRCC tumor tissues." (PMID 38831128, 2024). "Pre-analysis and experiments based on public databases and clinical samples revealed that SCGN was not expressed in normal renal tissues and was highly expressed in tumor tissues, but its expression was gradually absent with tumor progression and metastasis." (PMID 39664565, 2024). "Subsequently, we analyzed SCGN expression in 6 paired ccRCC and adjacent normal tissues as well as in cell lines, and consistently with our previous findings SCGN was highly expressed in tumor tissues, and expression was absent as the nuclear level increased." (PMID 39664565, 2024). "However, with tumor progression and distant metastasis of the ccRCC, the expression of SCGN is gradually absent." (PMID 39664565, 2024).
endocrinopathies (1 paper, 2019). "Intriguingly, despite the restricted expression of SCGN in neuroendocrine lineages, there were no overt endocrinopathies or neurologic phenotypes." (PMID 31663849, 2019).
neurodegenerative disease (1 paper, 2022). A disorder of the central nervous system characterized by gradual and progressive loss of neural tissue and neurologic function. "The interplay between stress, neurodegenerative diseases, and SCGN expression was unclear for a long time." (PMID 35870554, 2022).
SCGN also shares sentences with these, for which no sentence is quoted: autism (2 papers); allergic asthma (1); dyslipidemia (1); intellectual disabilities (1); metabolic disorders (1); myxoma (1); Parkinson’s (1); small cell lung carcinoma (1).